SPRYD7 (SPRY domain containing 7)
Synonyms: C13orf1; CLLD6
Tractability: PROTAC: ubiquitination databases record sites on it; its protein half-life has been measured.
Gene: Protein-coding gene on chromosome 13 (49,912,702 to 49,936,490, reverse strand). Ensembl gene ENSG00000123178.
Subcellular location (Human Protein Atlas): Vesicles
Gene Ontology:
Molecular function: protein binding
Genetic constraint (gnomAD): Loss-of-function variants: 4 observed, 8.95 expected, observed/expected ratio (o/e) 0.45, 90% interval 0.22 to 1.02. That is too few expected variants to judge how well the gene tolerates losing a copy. Missense variants: 98 observed, 113.75 expected, observed/expected ratio (o/e) 0.86, 90% interval 0.73 to 1.02. Synonymous variants: 42 observed, 42.7 expected, observed/expected ratio (o/e) 0.98, 90% interval 0.77 to 1.27.
Homologues: Orthologues: chimpanzee SPRYD7 (99% identical), macaque SPRYD7 (99% identical), mouse Spryd7 (98% identical), rabbit SPRYD7 (98% identical), dog SPRYD7 (97% identical), rat Spryd7 (97% identical), guinea pig SPRYD7 (86% identical), pig SPRYD7 (86% identical), zebrafish spryd7b (85% identical), zebrafish spryd7a (82% identical), tropical clawed frog spryd7 (80% identical), Drosophila melanogaster CG7785 (47% identical), and 1 more.
Diseases named in the same sentence as SPRYD7 in open-access papers:
SPRYD7 is named in the same sentence as 10 diseases in open-access papers, as found by Europe PMC text mining. Sharing a sentence is not in itself a finding about the gene and the disease. The quoted sentences say what the papers report.
colorectal cancer (1 paper, 2023). A primary or metastatic malignant neoplasm that affects the colon or rectum. "SPRY domain-containing protein 7 (SPRYD7) is a barely known protein identified via spatial proteomics as being upregulated in highly metastatic-to-liver KM12SM colorectal cancer (CRC) cells in comparison to its isogenic poorly metastatic KM12C CRC cells." (PMID 37947626, 2023).
lipoma (1 paper, 2024). A benign, usually painless, well-circumscribed lipomatous tumor composed of adipose tissue. "Therefore, genes known to be related to lipomas were also considered as potential candidate genes, and included SPRYD7, LHFPL6, RCBTB2, RCBTB1, and CDK4." (PMID 39719593, 2024).
prostate tumour (1 paper, 2013). "ARLTS1 and MLNR had a correlation value of −0.35 (p-value 0.04) in PCa cell lines, and ARLTS1 and SPRYD7 had a correlation value of −0.34 (p-value 0.003) in prostate tumour specimens." (PMID 23940804, 2013). "Our finding of the eSNP in the SPRYD7 gene was endorsed in the co-expression data, in which the ARLTS1 expression levels were significantly correlated with SPRYD7 expression, and in the prostate tumour specimens." (PMID 23940804, 2013).
rectum adenocarcinoma (1 paper, 2023). An adenocarcinoma arising from the rectum. "At the mRNA level, from analysis of the GSE17538 cohort containing colon and rectum adenocarcinoma samples, high expression of SPRYD7 was significantly associated with the poor survival of CRC patients (p-value = 0.00016)." (PMID 37947626, 2023).
tumor (3 papers, 2013 to 2025). "Then, the subcutaneous inoculation of SPRYD7-stably transfected cells and mock cells was performed to evaluate in vivo alterations in the tumor growth associated with SPRYD7 overexpression." (PMID 37947626, 2023). "Furthermore, based on our results, SPRYD7 was observed to favor liver homing and tumor growth in vivo and to induce cell migration and invasion, which might also be associated with the high blood-vessel-formation capacity of cells overexpressing SPRYD7." (PMID 37947626, 2023). "Finally, higher mRNA levels of SPRYD7 were found in tumor tissue samples of CRC patients in comparison to paired non-tumoral tissues." (PMID 37947626, 2023). "In addition, SPRYD7-stably transfected KM12C cells almost equaled the tumor growth ability of KM12SM control cells." (PMID 37947626, 2023). "Upon upregulation of SPRYD7, in vitro and in vivo functional assays confirmed a key role of SPRYD7 in the invasion and migration of CRC cells and in liver homing and tumor growth." (PMID 37947626, 2023). "Moreover, higher mRNA levels of SPRYD7 were found in SW48 and Lim-1215 CRC cells derived from a stage-IV tumor and a metastatic site, respectively, in comparison to poorly metastatic HT-29, Caco-2, and RKO CRC cells." (PMID 37947626, 2023). "The third eSNP gene, SPRYD7, (SPRY domain containing 7/chromosome 13 open reading frame 1 [C13or1]) also known as chronic lymphocytic deletion region gene 6 protein, (CLLD6), is proposed to have a tumour suppressor function because it has been detected to be downregulated in B-CLL patients." (PMID 23940804, 2013).
cancer (2 papers, 2023 to 2025). A tumor composed of atypical neoplastic, often pleomorphic cells that invade other tissues. "In this sense, several of the proteins modulated or interacting with SPRYD7 described here have previously been associated with angiogenesis, inflammation, and cancer." (PMID 37947626, 2023).
SPRYD7 also shares sentences with these, for which no sentence is quoted: dyslipidemia (1 paper); lymphocytic leukemia (1); melanoma (1); tuberculosis (1).